MIR455 (microRNA 455)
Synonyms: hsa-mir-455; MIRN455; mir-455
Gene: MicroRNA gene on chromosome 9 (114,209,434 to 114,209,529, forward strand). Ensembl gene ENSG00000207726.
Gene Ontology:
Biological process: cellular response to amino acid stimulus; cellular response to leukemia inhibitory factor; male sex differentiation; miRNA-mediated post-transcriptional gene silencing; sensory perception of sound
Cellular component: RISC complex
Homologues: Orthologues: chimpanzee ptr-mir-455 (100% identical), macaque mml-mir-455 (100% identical), pig MIR455 (100% identical), rabbit MIR455 (100% identical), zebrafish dre-mir-455-1 (95% identical), zebrafish mir455b (89% identical), tropical clawed frog xtr-mir-455 (88% identical), guinea pig MIR455 (85% identical), mouse Mir455 (79% identical), rat Mir455 (77% identical).